FBXL20 (F-box and leucine rich repeat protein 20)
Description:
Substrate-recognition component of the SCF (SKP1-CUL1-F-box protein)-type E3 ubiquitin ligase complex. Role in neural transmission (By similarity).
Synonyms: FBL2; MGC15482; Fbl20
Tractability: PROTAC: ubiquitination databases record sites on it; its protein half-life has been measured.
Gene: Protein-coding gene on chromosome 17 (39,252,663 to 39,402,523, reverse strand). Ensembl gene ENSG00000108306.
Subcellular location: Cytoplasm
Subcellular location (Human Protein Atlas): Microtubules
Pathways (Reactome):
Immune System: Antigen processing: Ubiquitination & Proteasome degradation
Metabolism of proteins: Neddylation
Gene Ontology:
Molecular function: protein binding
Biological process: SCF-dependent proteasomal ubiquitin-dependent protein catabolic process; regulation of protein catabolic process at presynapse, modulating synaptic transmission; regulation of synaptic vesicle exocytosis
Cellular component: cytosol; cytoplasm; glutamatergic synapse; presynapse; Schaffer collateral - CA1 synapse; synapse
Genetic constraint (gnomAD): Loss-of-function variants: 8 observed, 38.51 expected, observed/expected ratio (o/e) 0.21, 90% interval 0.12 to 0.38. The upper end of that interval is the gene's LOEUF score, 0.38, which puts it in group 1 of 6, group 1 being the genes least tolerant of losing a copy. Missense variants: 219 observed, 398.27 expected, observed/expected ratio (o/e) 0.55, 90% interval 0.49 to 0.62. Synonymous variants: 141 observed, 152.25 expected, observed/expected ratio (o/e) 0.93, 90% interval 0.81 to 1.07.
Homologues: Orthologues: guinea pig FBXL20 (100% identical), mouse Fbxl20 (99% identical), chimpanzee FBXL20 (97% identical), dog FBXL20 (97% identical), rat Fbxl20 (97% identical), rabbit FBXL20 (97% identical), macaque FBXL20 (94% identical), tropical clawed frog fbxl20 (94% identical), zebrafish fbxl20 (92% identical), pig FBXL20 (81% identical), Drosophila melanogaster CG9003 (59% identical), Caenorhabditis elegans fbxl-1 (47% identical), and 24 more. Paralogues in human: FBXL2 (76% identical), FBXL13 (25% identical), FBXL7 (24% identical), FBXL18 (22% identical), FBXL4 (22% identical), FBXL5 (22% identical), FBXL16 (21% identical), FBXL14 (20% identical), FBXL6 (20% identical), FBXL3 (18% identical), SKP2 (18% identical), FBXL19 (17% identical), and 3 more.
Diseases named in the same sentence as FBXL20 in open-access papers:
FBXL20 is named in the same sentence as 16 diseases in open-access papers, as found by Europe PMC text mining. Sharing a sentence is not in itself a finding about the gene and the disease. The quoted sentences say what the papers report.
bladder cancer (1 paper, 2021). "Five genes are amplified in > 5% of the corresponding TCGA cohorts: E2F3 (cytoband 6p22.3, 15.7% of bladder cancer), TFRC (3q29, 13.0% of head and neck cancers), MFSD3 (8q24.3, 7.9% of head and neck cancers, FKBP4 (12p13.33, 6.8% of ovarian carcinoma) and FBXL20 (17q12, 6.4% of gastric cancer)." (PMID 34313788, 2021).
breast carcinoma (1 paper, 2014). "For Breast cancer 6 genes had significant aCGH/expression correlation at a level of 0.05 in all 7 breast cancer data sets (BCL9, AZIN1, TAF2, YTHDF1, TTC13, FBXL20)." (PMID 25148247, 2014).
colon adenocarcinoma (1 paper, 2014). "Our previous study on FBXL20 showed that the gene was critical in the abnormal Wnt signaling pathway, as the β-catenin expression level was significantly decreased after silencing the FBXL20 gene in the colon adenocarcinoma SW480 and SW620 cells." (PMID 24932313, 2014).
colorectal adenocarcinoma (1 paper, 2014). The most common type of colorectal carcinoma. "Although, it was shown that the SET expression level was markedly increased following silencing of the FBXL20 gene in the colorectal adenocarcinoma cell lines, SW480 and SW620." (PMID 24932313, 2014). "The mechanisms eliciting colorectal adenocarcinoma are not well understood and the FBXL20 gene is problematic as it exhibits an abnormal expression in colorectal cancer cells." (PMID 24932313, 2014). "In conclusion, the present data on the roles of FBXL20 in colorectal adenocarcinoma cells are comparable with other F-Box family members, which mediate the specific substrate protein into the ubiquitin proteasome pathway." (PMID 24932313, 2014). "In addition, the E-cadherin and SET expression levels were markedly upregulated when the FBXL20 gene was knocked out in colorectal adenocarcinoma." (PMID 24932313, 2014). "The mechanism by which the upregulated FBXL20 expression level leads to the increased proliferation of the colorectal adenocarcinoma cells remains unknown." (PMID 24932313, 2014). "However, further studies are required to identify all of the factors that are involved in the FBXL20-mediated ubiquitin proteasome process in colorectal adenocarcinoma." (PMID 24932313, 2014).
depression (1 paper, 2021). "In this study, we found three of these predictive PPD genes (TMEM189, GALNT10 and FBXL20) were also associated with PPD onset in the current study and not with depression per se." (PMID 33664235, 2021). "From these, three genes (TMEM189, GALNT10 and FBXL20) were also associated with PPD onset in this study and not with depression per se (enrichment P = 0.08, indicating no significant overlap than expected by chance)." (PMID 33664235, 2021).
heart failure (1 paper, 2021). Inability of the heart to pump blood at an adequate rate to meet tissue metabolic requirements. "Reduced autophagy contributes to accelerated cardiac ageing and heart failure, and may serve as a link between FBXL20 and CHF." (PMID 34616426, 2021).
Infertility (1 paper, 2024). "Another identified gene, FBXL20, plays a role in inflammatory responses which can be detrimental to spermatozoa and ultimately lead to infertility." (PMID 39411484, 2024).
Obesity (1 paper, 2023). Accumulation of substantial excess body fat. "PTGS2 and TNFAIP3 were identified as hypomethylated-high-expression genes and FBXL20 as a hypermethylated-low expression gene in SAT of individuals with obesity." (PMID 37252693, 2023). "We considered the three most connective nodes as hub-bottleneck genes: prostaglandin-endoperoxide synthase 2 ( PTGS2 ), tumor necrosis factor α-induced protein 3 ( TNFAIP3 ), and F-box and leucine rich repeat protein 20 ( FBXL20 ), which might play a critical role in obesity." (PMID 37252693, 2023). "However, FBXL20 has not yet been associated with obesity or its related comorbidities." (PMID 37252693, 2023). "Thus, FBXL20 and TNFAIP3 could be new candidate genes to be studied in the context of obesity." (PMID 37252693, 2023).
cancer (3 papers, 2024 to 2025). A tumor composed of atypical neoplastic, often pleomorphic cells that invade other tissues. "On the other hand, FBXL20 has been linked to chemotherapy resistance in cancer, while the suppression of STARD3 expression induces cell death in BC, and its high expression is associated with poorer survival." (PMID 40136626, 2025). "The high-level expression of FBXL20 in cancer cells, which reduces therapeutic drug-induced apoptosis and promotes chemoresistance, identifies it as a critical target." (PMID 40841912, 2025). "More specifically regarding the UPS, RNAi-mediated ablation of FBXL20, an F-box protein that is part of an E3 ligase complex, results in increased levels of Puma as well as Bax, which further enhances the sensitivity of cancer cells to chemotherapeutic drugs." (PMID 40841912, 2025). "Therefore, the importance of targeting FBXL20 in cancers in conjunction with chemotherapy may represent a promising anticancer strategy to overcome chemoresistance." (PMID 40841912, 2025).
tumor (2 papers, 2015 to 2023). "While the expression levels of GRB7, MIEN1, ERBB2 and FBXL20 were considerably greater in tumour tissues than in normal tissues (p < 0.001 or p < 0.01), the expression levels of MED1 and CDK12 were significantly lower in tumour tissues than in normal tissues (p < 0.001)." (PMID 37525498, 2023).
neurodegenerative disease (1 paper, 2022). A disorder of the central nervous system characterized by gradual and progressive loss of neural tissue and neurologic function. "Combined with the expression levels in the brain and the supporting literature evidence related to neurodegenerative diseases in vivo and in vitro, we screened out FBXL20, PPP1R1B, NEUROD2 (NDF2), and ERBB2 (HER2) for follow-up molecular biology experiments." (PMID 35694256, 2022).
FBXL20 also shares sentences with these, for which no sentence is quoted: colon cancer (1 paper); colorectal cancer (1); gastric cancer (1); head and neck cancer (1); ovarian carcinoma (1).